INS (insulin)
Diseases named in the same sentence as INS in open-access papers (continued):
Sharing a sentence is not in itself a finding about the gene and the disease.
Insulin resistance (continued). "The high fasting proinsulin concentrations in the MO participants, indicating insulin resistance, were significantly lowered in the GBP group and similar to NW control subjects, indicating improved insulin sensitivity by the induced weight loss in the group treated with bariatric surgery." (PMID 17894830, 2007). "injection of insulin, demonstrating diet-induced insulin-resistance." (PMID 18070349, 2007). "However, the attenuation of the relation between CVD risk factors and IGR categories was only marginally larger upon adjustment with all three adiposity/insulin resistance markers (BMI, waist, insulin) as compared to adjustment for any of these markers." (PMID 17958881, 2007). "The analysis examines whether IGR categories predict IMT independently of age and CVD risk factors and whether an association, if any, would be sensitive to further adjustment of markers of adiposity or insulin resistance (BMI, waist, and insulin)." (PMID 17958881, 2007). "Interestingly, while systemic heterozygous IRS-2 deficiency improved insulin sensitivity, brain-specific IRS-2 knock out led to insulin resistance." (PMID 19412415, 2007). "CyclosetTM is a quick-release formulation of bromocriptine mesylate, a dopamine agonist, which in animal models of insulin resistance and type 2 diabetes acts centrally to reduce resistance to insulin- mediated suppression of hepatic glucose output and tissue glucose disposal." (PMID 17592632, 2007). "This study could provide insights to the role of insulin, insulin resistance, IGF-1 in carcinogenesis although a precise role and the extent of influence cannot be determined." (PMID 17953765, 2007). "Type 2 diabetes arises when insulin resistance-induced compensatory insulin secretion exhausts." (PMID 17786204, 2007). "As such, it may be thought of as beneficial for obesity and, at the same time, suggests that reduction in insulin directly or via carbohydrate restriction will improve insulin resistance." (PMID 17663761, 2007). "The mechanisms responsible for this clinical manifestation are still obscure, but two processes have been proposed: the pancreatic β-cell iron accumulation results in cell damage and diminished insulin secretion, and liver iron overload leads to insulin resistance." (PMID 17949489, 2007). "Should this hypothesis test positive, then it would be show insights to the role of insulin and insulin resistance in carcinogenesis." (PMID 17953765, 2007). "Of note, adult ob/ob mice compensated for their insulin resistance with increased insulin levels." (PMID 17465682, 2007). "Extreme SFA consumption (usually to the exclusion of dietary PUFA) is typically linked to insulin resistance, while other studies have reported that dietary SFA enhances insulin secretion more than dietary PUFA, a possibility suggested by our findings where POL diet had the lowest P/S ratio." (PMID 17224066, 2007). "However, a few associations were no longer significant upon full adjustment for adiposity and insulin resistance markers (BMI, waist, insulin)." (PMID 17958881, 2007). "The raised plasma insulin levels in insulin resistance may bring about this subtle transition as well." (PMID 17437648, 2007). "To examine whether dmpk−/− mice display muscle insulin resistance, we first measured insulin-stimulated glucose transport in cardiac and skeletal muscle." (PMID 17987120, 2007). "In keeping with this we have shown that mice lacking RIP140 are protected from the insulin resistance associated with high-fat feeding or aging and this is due to an increase in insulin sensitivity." (PMID 17767910, 2007). "Previously we have demonstrated that CAR could improve insulin action in the fructose-fed rat model of insulin resistance." (PMID 17641743, 2007). "These alterations may result from a direct effect of E2 and BPA on β-cell insulin content, or a compensatory response resulting from the insulin resistance noted in these animals, or both." (PMID 16393666, 2006).
Insulin resistance (continued). "In addition, the altered glucose and insulin tolerance test results were consistent with the fact that these mice had developed insulin resistance." (PMID 16393666, 2006). "According to the American Diabetes Association Consensus Development Conference on insulin resistance, it is one of the only two methods (the other one is the euglycemic insulin clamp) that are recommended for assessing peripheral insulin resistance due to their satisfactory, consistent performance." (PMID 16842624, 2006). "It has been hypothesized that peripheral insulin resistance can affect CNS insulin levels, cognition and amyloid beta levels." (PMID 17096857, 2006). "The positive action of the insulin-sensitizing treatments could be explained by a decrease in the peripheral insulin resistance but also by a direct action at the ovarian level." (PMID 17347533, 2006). "In addition, several studies have demonstrated that the hypersecretion of insulin is a primary defect of type 2 diabetes and that insulin resistance develops secondarily to the chronic hyperinsulinemia." (PMID 16393666, 2006). "Therefore, it is possible that multiple mechanisms can contribute to insulin resistance and thus impair insulin-mediated signal transduction, and reversal of one of them can improve insulin action, as have been previously reported." (PMID 16729893, 2006). "Because skeletal muscle is the largest insulin-sensitive organ in humans, NO-induced insulin resistance in this tissue will have a major impact on whole body glucose homeostasis, especially in patients who are obese or need to take NO drugs for prolonged periods." (PMID 16729893, 2006). "High carbohydrate diets, by increasing the insulin secretion, may worsen insulin resistance in diabetic patients and increase the inflammatory and prothrombotic tendencies in this patient population." (PMID 16018812, 2005). "Insulin resistance may be defined as a diminished response to the biological actions of insulin; it may involve not only the carbohydrate metabolism, but also the lipid metabolism." (PMID 15963228, 2005). "Rats on the HF diet for 4 weeks showed marked insulin resistance and dyslipidemia, indicated by significant increases in postprandial serum levels of triglycerides, free fatty acids, insulin, and area under curve (AUC) for serum insulin during OGTT." (PMID 15491498, 2004). "Paradoxically, the TZDs can lead to weight gain while improving insulin sensitivity as the new SCAT adipocytes continue to trap FA and as fat storage continues, eventually the new adipocytes will enlarge, become less insulin sensitive, and ultimately contribute to insulin resistance." (PMID 15530168, 2004). "Decreased adipose tissue deposition by decreasing lipogenesis and increasing lipolysis may help to prevent insulin resistance (by reducing body fat) and the estrogenic actions of dietary phytoestrogens may augment the efficiency of insulin." (PMID 15617573, 2004). "Insulin resistance along with other conditions of syndrome X might induce hypertension by a host of mechanisms involving insulin itself, increased sodium reabsorption and/or enhanced intra cellular concentration of free calcium in vascular smooth muscle." (PMID 15287987, 2004). "This study demonstrates that LA can alter lipid metabolism in fructose-fed insulin-resistant rats and may have implications in the treatment of insulin resistance." (PMID 15512787, 2004). "In diabetic people, elevated insulin secretion cannot compensate for increased insulin resistance." (PMID 15706798, 1998). "lactis CECT 8145) with insulin sensitizing, antiadipogenic, and antihypertensive effects, may beneficially modulate gut microbiota and host signaling pathways, including Akt phosphorylation, thereby ameliorating insulin resistance and vascular dysfunction." (PMID 41596333, 2026).
Insulin resistance (continued). "Although numerous studies have explored how excessive protein intake may induce insulin resistance and T2D, the effects of chronic HP intake on insulin sensitivity and blood glucose levels in healthy populations remain unclear; moreover, its role in glucose homeostasis remains undefined." (PMID 41388732, 2026). "Considering these results together, the hyperglycemia observed prior to admission may have indicated cortisol-induced insulin resistance, whereas the nocturnal hypoglycemia after admission may have been a consequence of reduced cortisol secretion and subsequent improvement in insulin sensitivity." (PMID 41536580, 2026). "D-galactose promotes insulin resistance (IR) and neurodegeneration through hyperglycemia, advanced glycation end products (AGEs), oxidative stress, amyloid-β accumulation, and disruption of the insulin signalling pathway, leading to neuroinflammation and neuroapoptosis." (PMID 42255438, 2026). "Moreover, adipocyte-derived CLU has been shown to inhibit insulin signaling in the liver, thereby increasing gluconeogenesis, and may function as both a marker and a facilitator of insulin resistance." (PMID 41515662, 2026). "On the other hand, endogenous insulin secretion may be intact in individuals with T2D, and nutritional guidelines for this population aim to minimize postprandial insulin surges, as a high blood insulin concentration may promote insulin resistance and/or excessive weight gain." (PMID 41602572, 2026). "The significant improvements in glycemic control parameters (FBG, HOMA‐IR, serum insulin) and lipid profiles suggest that Sumac may be particularly beneficial for patients with insulin resistance and dyslipidemia, potentially reducing their overall cardiovascular risk burden." (PMID 41329614, 2026). "Additionally, a causative role for increased insulin secretion in obesity, independent of insulin resistance, is suggested by functional and genetic data in humans." (PMID 41386533, 2026). "In addition, SGLT2 inhibitor mitigated insulin resistance in insulin target tissues." (PMID 41585322, 2026). "Moreover, the chronic elevation in circulating insulin which may accompany a long-term high protein diet, could further promote insulin resistance, worsening the diseases’ severity." (PMID 41602572, 2026). "Therefore, its diminished postprandial response may be linked to the hypersecretion of insulin observed in individuals with T2DM and insulin resistance." (PMID 41575482, 2026). "For example, F can affect glucose metabolism, with prolonged exposure potentially leading to insulin resistance and impaired glucose tolerance, it can interfere with the function of pancreatic beta cells and may also influence the insulin signaling pathway, contributing to insulin resistance." (PMID 41524939, 2026). "Extending these investigations to skeletal muscle, characterizing the involvement of LRRC8A in insulin resistance, including its interactions with glucose transporters and insulin signaling components, may uncover previously unrecognized mechanisms underlying systemic metabolic dysfunction." (PMID 41439137, 2026). "Moreover, CR lowers circulating insulin, which may contribute to the CR-induced mitigation of cellular senescence and insulin resistance." (PMID 41189469, 2026). "To the contrary, we used the surrogate parameter of HOMA-IR calculation instead of direct measurement of insulin resistance, which has some limitations; eg, HOMA-IR is associated primarily with hepatic insulin resistance and not with peripheral tissue insulin sensitivity." (PMID 40580113, 2025). "Also, Alloprevotella had a negative association with serum lipids, insulin, fasting blood glucose, homeostatic model assessment for insulin resistance (HOMA‐IR), liver TG, as well as mRNA levels of NLRP3, NF‐κB, and Caspase‐1." (PMID 40071130, 2025).
Insulin resistance (continued). "Neuropsychological impairments observed in youths with insulin resistance or type 2 diabetes are thought to result from a combination of factors, including chronic hyperglycemia, systemic inflammation, vascular dysfunction, and disrupted insulin signaling within the brain." (PMID 41464558, 2025). "However, the precise role of mitochondrial control of inflammation in the pathogenesis of insulin resistance remains unclear, though it provides a potential mechanism through which mitochondrial dysfunction may affect insulin action." (PMID 39966707, 2025). "However, in cells with prior insulin resistance, dexamethasone did not cause a further reduction in insulin sensitivity (possibly because levels had been reduced to a basal level)." (PMID 40422898, 2025). "However, leptin and insulin resistance are common in obesity, where the effects of leptin and insulin within the AC, and especially in the POMC/CART neurons, become less pronounced and sometimes these effects may even be absent." (PMID 40136445, 2025). "Similarly, a positive and significant correlation was found between Apo‐B and body weight (r = 0.423, p < 0.001), BMI (r = 0.425, p < 0.001), body fat percentage (r = 0.329, p < 0.001), insulin resistance (r = 0.653, p < 0.001), and fasting insulin concentrations (r = 0.637, p < 0.001)." (PMID 40123054, 2025). "Moreover, our findings highlight that elevated TG levels are not exclusively a sign of insulin resistance but are also associated with worse glycemic control in insulin-dependent patients." (PMID 40076685, 2025). "Obesity and increased WC are determinants of insulin resistance, but due to the disease's pathogenesis involving compensatory beta-cell function and subsequent increased insulin secretion, the time until beta-cell failure and the consequent development of T2DM may be delayed." (PMID 39147370, 2025). "Additionally, the predictive accuracy of the traditional homeostasis model assessment for insulin resistance (HOMA-IR) might be affected in patients receiving insulin therapy or those with impaired beta-cell function." (PMID 40810068, 2025). "In conclusion, we believe that GDM is mainly associated with insulin resistance during pregnancy, and the low ratio of AST/ALT may reflect the predisposition of the liver to low insulin sensitivity at this stage due to insufficient metabolic demand as well as mild injury." (PMID 40880520, 2025). "In addition to impaired insulin secretion, insulin resistance also plays a significant role." (PMID 40075815, 2025). "Further studies are needed to unravel additional factors that influence the development of insulin resistance under fasting and postprandial states in apparently healthy adults in our setting even as health educational measures on lifestyle changes that improve insulin sensitivity are intensified." (PMID 40273152, 2025). "In mice with diet-induced insulin resistance, impaired insulin signaling may reduce TUG cleavage." (PMID 40631311, 2025). "Thus, reducing insulin resistance, hyperinsulinemia, and insulin dose may all be important therapeutic targets in the treatment of type 1 diabetes." (PMID 41285865, 2025). "Moreover, ROS may contribute to diseases such as type 2 diabetes by activating alternative downstream signaling pathways that are critically involved in insulin resistance and impaired insulin secretion." (PMID 40732969, 2025). "In type 2 diabetes, reduced glucose transport through normal insulin stimulation leads to increased intracellular free calcium concentration, increasing the demand for insulin, resulting in excessive insulin production and secretion, leading to insulin resistance mediated by hyperparathyroidism." (PMID 40248148, 2025). "In a sub-group analysis based on past COVID-19 status, only the levels of fasting plasma glucose, insulin and total cholesterol could significantly (P < 0.05) associate with insulin resistance in participants without past COVID-19 status." (PMID 40273152, 2025).
Insulin resistance (continued). "Overexpression of miR-20b-5p and miR-106a-5p in serum EVs in insulin-resistant PCOS mouse models could reduce adipocyte differentiation, thereby alleviating lipid metabolism disorders during the process of PCOS development caused by insulin resistance." (PMID 41358005, 2025). "Pre-clinical evidence in mice suggests that Metrnl expression in adipocytes may improve insulin sensitivity via the activation of the peroxisome proliferator-activated receptor gamma (PPARγ) pathway, which is crucial for managing insulin resistance and adipocyte differentiation." (PMID 40559404, 2025). "Insulin resistance, a cardinal pathological feature of metabolic dysregulation, is characterized by progressive impairment of insulin-mediated glucose uptake and utilization in peripheral tissues, often occurring under normal or elevated circulating insulin levels." (PMID 40703260, 2025). "Furthermore, the inflammatory state associated with metabolic syndrome modulates iron metabolism and dysregulation of iron, in turn, modulates immune responses, creating a feedback loop that improves chronic insulin resistance and disrupts insulin-mediated glucose uptake." (PMID 39941760, 2025). "However, these strains are less optimal for prospectively tracking the gradual transition from insulin sensitivity to insulin resistance, because IR arises early in life and progresses rapidly from a fixed genetic lesion with a minimal insulin-sensitive baseline and limited control over timing." (PMID 41002949, 2025). "However, an examination of the relationship between ZAG and insulin resistance using the euglycemic-hyperinsulinemic clamp, a method involving a controlled and rapid infusion of insulin to maintain constant blood glucose levels, yielded results that were surprising and discordant with ours." (PMID 40564902, 2025). "Interestingly, insulin at fasting and below fasting levels seems to regulate brain glucose uptake, a response that is attenuated in persons with insulin resistance, indicating the presence of brain and concurrent peripheral insulin resistance." (PMID 39185744, 2025). "A bidirectional connection between insulin resistance and defective autophagy is also proposed; thus, we can speculate the paramount importance of autophagy induction in the insulin-sensitizing and neuroprotective effects of resveratrol and monomethyl resveratrol." (PMID 41226821, 2025). "Additionally, estrogen plays a role in reducing inflammation and enhancing insulin sensitivity, but its decline after menopause may worsen insulin resistance and disrupt uric acid metabolism." (PMID 40607233, 2025). "Additionally, the inhibition of the RAAS by vitamin D may enhance insulin sensitivity in peripheral tissues such as skeletal muscle and adipose tissue, thereby improving glucose uptake and reducing insulin resistance." (PMID 40284166, 2025). "Likewise, in the current study, diminished brain insulin responsiveness in the hippocampus was present without notable perturbations in peripheral metabolism, suggesting that diet-induced changes in brain insulin responsiveness precede peripheral insulin resistance." (PMID 39984682, 2025). "Thus, integrating the high peripheral insulin-induced insulin resistance into the insulin sensitivity function could enhance the model’s capability of capturing the insulin dynamics of SWNA." (PMID 40568093, 2025). "Additionally, insulin signaling pathways like insulin receptor substrate 1, Protein kinase C, and Ak strain transforming were suppressed in murine liver cells by TFAs, indicating hepatic insulin signaling impairment, which reflects insulin resistance and aggravates hepatic steatosis." (PMID 41373860, 2025). "Moreover, it is known to be insulin-responsive and is recognized as a convenient and effective model for studying several attributes of muscle physiology during health and disease including insulin resistance." (PMID 41305671, 2025).